HNRNPCL2 (heterogeneous nuclear ribonucleoprotein C like 2)
Description:
May play a role in nucleosome assembly by neutralizing basic proteins such as A and B core hnRNPs.
Synonyms: HNRNPCP5
Tractability: PROTAC: ubiquitination databases record sites on it.
Gene: Protein-coding gene on chromosome 1 (13,115,488 to 13,116,854, reverse strand). Ensembl gene ENSG00000275774.
Subcellular location: Nucleus
Subcellular location (Human Protein Atlas): Nucleoplasm
Gene Ontology:
Molecular function: identical protein binding; protein binding; RNA binding; nucleic acid binding
Cellular component: nucleus
Genetic constraint (gnomAD): Loss-of-function variants: 17 observed, 18.64 expected, observed/expected ratio (o/e) 0.91, 90% interval 0.62 to 1.37. The upper end of that interval is the gene's LOEUF score, 1.37, which puts it in group 5 of 6, group 1 being the genes least tolerant of losing a copy. Missense variants: 358 observed, 350.56 expected, observed/expected ratio (o/e) 1.02, 90% interval 0.94 to 1.12. Synonymous variants: 133 observed, 124.51 expected, observed/expected ratio (o/e) 1.07, 90% interval 0.93 to 1.23.
Homologues: Orthologues: rabbit HNRNPC (88% identical), mouse Hnrnpc (87% identical), rat LOC100911576 (87% identical), tropical clawed frog hnrnpc (74% identical). Paralogues in human: HNRNPCL1 (96% identical), HNRNPCL3 (92% identical), HNRNPCL4 (92% identical), HNRNPC (88% identical), RALYL (45% identical), RALY (43% identical).
Diseases named in the same sentence as HNRNPCL2 in open-access papers:
HNRNPCL2 is named in the same sentence as 5 diseases in open-access papers, as found by Europe PMC text mining. Sharing a sentence is not in itself a finding about the gene and the disease. The quoted sentences say what the papers report.
cervical cancer (1 paper, 2022). A primary or metastatic malignant neoplasm involving the cervix. "Univariate Cox regression analysis screened 7 genes (FZR1, IMPDH1, HNRNPCL2, PCNA, GPKOW, XPA, and DDX39A) that were associated with the cervical cancer prognosis." (PMID 35909901, 2022).
HNRNPCL2 also shares sentences with these, for which no sentence is quoted: cancer (1 paper); follicular thyroid adenoma (1); thyroid cancer (1); tumor (1).